TXNDC8 (thioredoxin domain containing 8)
Description:
May be required for post-translational modifications of proteins required for acrosomal biogenesis. May act by reducing disulfide bonds within the sperm.
Synonyms: Sptrx-3; SPTRX3; TRX6; bA427L11.2
Tractability: No criterion of Open Targets' tractability assessment is met for any kind of drug.
Gene: Protein-coding gene on chromosome 9 (110,303,476 to 110,337,891, reverse strand). Ensembl gene ENSG00000204193.
Subcellular location: Cytoplasm; Golgi apparatus
Gene Ontology:
Molecular function: protein-disulfide reductase activity
Biological process: spermatogenesis
Cellular component: cytoplasm; extracellular exosome; Golgi apparatus; acrosomal vesicle; endomembrane system
Genetic constraint (gnomAD): Loss-of-function variants: 8 observed, 7.77 expected, observed/expected ratio (o/e) 1.03, 90% interval 0.6 to 1.75. That is too few expected variants to judge how well the gene tolerates losing a copy. Missense variants: 112 observed, 105.39 expected, observed/expected ratio (o/e) 1.06, 90% interval 0.91 to 1.24. Synonymous variants: 39 observed, 34.19 expected, observed/expected ratio (o/e) 1.14, 90% interval 0.88 to 1.49.
Homologues: Orthologues: chimpanzee TXNDC8 (87% identical), macaque TXNDC8 (80% identical), rabbit TXNDC8 (76% identical), dog TXNDC8 (71% identical), mouse Txndc8 (63% identical), rat Txndc8 (62% identical), pig TXNDC8 (54% identical), Drosophila melanogaster CG14221 (24% identical). Paralogues in human: TXN (42% identical), TXNDC2 (36% identical), TXNL1 (35% identical), TXN2 (24% identical).
Diseases named in the same sentence as TXNDC8 in open-access papers:
TXNDC8 is named in the same sentence as 10 diseases in open-access papers, as found by Europe PMC text mining. Sharing a sentence is not in itself a finding about the gene and the disease. The quoted sentences say what the papers report.
male infertility (3 papers, 2013 to 2022). The inability of the male to effect fertilization of an ovum after a specified period of unprotected intercourse. "Notably, TXNDC8 is highly expressed in immature spermatozoa, which protects sperm cells against oxidative stress and its expression in mature spermatozoa is suggested as a potential marker for male infertility." (PMID 33233438, 2020).
colon cancer (1 paper, 2016). "Considering also the highest expression in adjacent tissues, three more genes show an agreement between expression and pathology location (the endometrial cancer genes MORC4 and TXNDC8 most highly expressed in the myometrium and colon cancer gene CDC27 most highly expressed in the ileum)." (PMID 26856619, 2016).
TXNDC8 also shares sentences with these, for which no sentence is quoted: asthenozoospermia (1 paper); Azoospermia (1); cancer (1); endometrial cancer (1); female-only infertility (1); Infertility (1); oligospermia (1); Sertoli Cell-Only Syndrome (1).